PRLR (prolactin receptor)
Description:
This is a receptor for the anterior pituitary hormone prolactin (PRL). Acts as a prosurvival factor for spermatozoa by inhibiting sperm capacitation through suppression of SRC kinase activation and stimulation of AKT. Isoform 4 is unable to transduce prolactin signaling. Isoform 6 is unable to transduce prolactin signaling.
Synonyms: HPRL; MFAB; RI-PRLR; hPRLrI
Tractability: Small molecule: a high-quality ligand is known. Antibody: its Gene Ontology location is reachable by antibodies, with high confidence; UniProt places it where antibodies can reach, with medium confidence; UniProt predicts a signal peptide or a membrane-spanning region. PROTAC: a small molecule that binds it is known.
Gene: Protein-coding gene on chromosome 5 (35,048,756 to 35,230,533, reverse strand). Ensembl gene ENSG00000113494.
Subcellular location: Membrane; Secreted (Isoform 7)
Pathways (Reactome):
Immune System: Growth hormone receptor signaling; Prolactin receptor signaling
Gene Ontology:
Molecular function: lipid binding; peptide hormone binding; prolactin receptor activity; protein binding; cytokine binding; cytokine receptor activity; protein kinase binding
Biological process: activation of Janus kinase activity; activation of transmembrane receptor protein tyrosine kinase activity; negative regulation of apoptotic process; cytokine-mediated signaling pathway; embryo implantation; lactation; positive regulation of cell population proliferation; positive regulation of cold-induced thermogenesis; steroid biosynthetic process; cellular response to granulocyte macrophage colony-stimulating factor stimulus; positive regulation of B cell proliferation; prolactin signaling pathway
Cellular component: cell surface; endosome lumen; external side of plasma membrane; plasma membrane; receptor complex; extracellular region; membrane
Genetic constraint (gnomAD): Loss-of-function variants: 11 observed, 41.54 expected, observed/expected ratio (o/e) 0.26, 90% interval 0.17 to 0.44. The upper end of that interval is the gene's LOEUF score, 0.44, which puts it in group 1 of 6, group 1 being the genes least tolerant of losing a copy. Missense variants: 652 observed, 779.14 expected, observed/expected ratio (o/e) 0.84, 90% interval 0.78 to 0.89. Synonymous variants: 269 observed, 291.63 expected, observed/expected ratio (o/e) 0.92, 90% interval 0.83 to 1.02.
Homologues: Orthologues: chimpanzee PRLR (100% identical), macaque PRLR (96% identical), rabbit PRLR (76% identical), dog PRLR (75% identical), pig PRLR (72% identical), rat Prlr (68% identical), mouse Prlr (68% identical), guinea pig PRLR (66% identical), tropical clawed frog prlr (41% identical), zebrafish prlra (32% identical), zebrafish prlrb (26% identical). Paralogues in human: GHR (21% identical), IL6ST (15% identical), IL12RB2 (13% identical), CSF3R (13% identical), LIFR (13% identical), IL23R (12% identical), LEPR (12% identical), OSMR (12% identical), CRLF1 (12% identical), IL31RA (12% identical), IL27RA (11% identical), IL12RB1 (10% identical), and 11 more.
Diseases named in the same sentence as PRLR in open-access papers:
PRLR is named in the same sentence as 147 diseases in open-access papers, as found by Europe PMC text mining. Sharing a sentence is not in itself a finding about the gene and the disease. The quoted sentences say what the papers report.
breast cancer (121 papers, 1990 to 2025). A primary or metastatic malignant neoplasm involving the breast. "An important effect of loss of PRLR expression in HR + MCF7 breast cancer cells were the promotion of luminal-to-basal conversion as measured by the loss of expression of the luminal markers CK18 and ER and the gain in stem cell marker CD44 expression." (PMID 40157909, 2025). "Aside from its biological relevance, emerging evidence suggests a possible association between PRLR-linked reproductive factors, such as breastfeeding duration, and breast cancer risk and prognosis." (PMID 40723262, 2025). "Correlation heatmap analysis and protein-protein interaction (PPI) network demonstrated strong associations among TNFSF4, TP63, CD24, ESR1, and PRLR, suggesting their potential roles in HR+ breast cancer progression." (PMID 40612672, 2025). "In conclusion, more studies are needed to understand the mechanisms that regulate PRLr expression and function, but the causal role of the PRLr signaling axis in the pathogenesis of breast carcinoma is well established." (PMID 40160874, 2025). "High-throughput RNA-seq data obtained from TCGA, Metabric and GEO datasets were analyzed to explore PRLR expression in breast cancer cell and the association of PRLR expression with tamoxifen treatment." (PMID 38898487, 2024). "Prolactin binding to the prolactin receptor (PRLR) can activate the transcription factor STAT5, thus, we examined the association between plasma prolactin and breast cancer risk by tumor expression of PRLR, STAT5, and the upstream kinase JAK2." (PMID 36882838, 2023). "Overall, we did not observe clear differences in the association of circulating prolactin levels and risk of breast cancer by expression of PRLR or downstream markers of prolactin receptor activation, pJAK2 and pSTAT5." (PMID 36882838, 2023). "PRLR, encoding the receptor for prolactin (which is also called luteotropin, and has been described as the third hormone in breast cancer) resembles ESR1 more than PGR in our study." (PMID 37789381, 2023). "We did not observe clear differences in the association between plasma prolactin and breast cancer risk by tumor expression of PRLR or pJAK2, although associations for premenopausal women were observed for pSTAT5 positive tumors only." (PMID 36882838, 2023). "In another study, SNPs were found in PRL, and PRLR genes were associated with breast cancer metastasis in Taiwanese women." (PMID 36187116, 2022). "Researchers have demonstrated in Yonezawa's study that the long PRLR associate with breast cancer metastasis by knocking down the long PRLR in two breast cancer models." (PMID 34651424, 2021). "Together, these results indicate that loss of PRLR expression in luminal/HR+ MCF-7 breast cancer cells results in their dedifferentiation to a basal-mesenchymal-like phenotype and further reduce their sensitivity to anti-hormonal therapy." (PMID 33446633, 2021). "Next, we examined the effects of loss of PRLR expression on the expression of different biomarkers of HR+ breast cancer subtype." (PMID 33446633, 2021). "Altogether these results demonstrate that loss of PRLR expression in HR+ breast cancer cells generates de-differentiated mesenchymal/basal-like proliferative tumors in vivo." (PMID 33446633, 2021). "Together, these results indicate that loss of PRLR expression in both breast cancer cell models fuels the generation of highly metastatic breast cancer cells." (PMID 33446633, 2021). "Next, we examined the effects of loss of PRLR expression in both breast cancer cell models on their metastatic properties in vivo." (PMID 33446633, 2021). "Next, using immune deficient cell line-derived xenograft mouse models (CDX), we assessed the effects of loss of PRLR expression in breast cancer cells on tumor development in vivo." (PMID 33446633, 2021).
breast cancer (continued). "Together, these results indicate that loss of PRLR expression in HER2-E breast cancer cells causes aberrant luminal and epithelial differentiation state with enhanced HER2 expression/activity and reduced sensitivity to HER2 targeted therapy." (PMID 33446633, 2021). "Together these results highlight that loss of PRLR expression in HER2-E breast cancer cells generates HER-2-driven aggressive epithelial, proliferative and highly vascular tumors in vivo." (PMID 33446633, 2021). "Collectively, these results reveal that loss PRLR expression alters the luminal and epithelial differentiation state of breast cancer cells in a subtype-dependent manner." (PMID 33446633, 2021). "These clinically challenging breast cancer cases are reminiscent of our findings where loss of PRLR expression in the HR+ MCF-7 cells switched them to a TNBC-like profile with high tumorigenic and metastatic capacities." (PMID 33446633, 2021). "In women, elevated levels of prolactin correlate with increased breast cancer risk and metastasis, whereas lower levels of prolactin/PRLR in clinical samples associate with improved patient survival." (PMID 33335078, 2020). "Despite the biological and clinical relevance of the prolactin/PRLR axis, incomplete knowledge of the underlying network has largely precluded its therapeutic exploitation in specific breast cancer subtypes." (PMID 33335078, 2020). "Together, these results indicate that loss of the co-expression of PRLR, TGFβRI and TGFβRII is indicative of aggressiveness and poor patient survival outcomes in breast cancer." (PMID 30987013, 2019). "In that study, two SNPs (rs7718468 and rs13436213) in the prolactin receptor (PRLR) gene were associated with breast cancer risk in postmenopausal women." (PMID 23095343, 2012). "Our data provide limited support for an association between common variations in PRLR and breast cancer risk." (PMID 21470416, 2011). "An association was detected for a region encompassing PRLR SNPs rs873456, rs7718468, rs34024951, and rs9292575 and postmenopausal breast cancer." (PMID 21470416, 2011). "To follow up our previous finding of a relationship between serum prolactin and breast cancer risk, we investigated the association between common genetic variation in PRL and PRLR and breast cancer risk in the Polish Breast Cancer Study." (PMID 21470416, 2011). "PRLR rs249537 was associated with breast cancer risk in premenopausal women; however, the minor allele homozygote genotype for rs249537 was rare (<1% in controls) and this association requires replication." (PMID 21470416, 2011). "We examined the association between SNPs in PRL and PRLR and breast cancer risk in a population of Polish women." (PMID 21470416, 2011). "We found limited evidence for a relationship between common genetic variants in PRL or PRLR and breast cancer." (PMID 21470416, 2011). "Estrogens and prolactin likely influence the risk of breast cancer by inducing cell proliferation and tumor growth through the ER and prolactin receptor, respectively." (PMID 22017816, 2011). "PRLR SNPs rs7718468 and rs13436213 were associated with postmenopausal breast cancer risk (rs7718468 per-allele OR 1.16, 95% CI 1.03 to 1.30; rs13436213 per-allele OR 1.13, 95% CI 1.01 to 1.26)." (PMID 21470416, 2011). "One SNP was associated with premenopausal breast cancer: PRLR rs249537 (per-allele OR 1.39, 95% CI 1.07 to 1.82)." (PMID 21470416, 2011). "We examined the association between variant alleles in 25 SNPs - 7 PRL and 18 PRLR - and breast cancer risk." (PMID 21470416, 2011). "While PRLR gene mutations have yet to be identified in the majority of breast cancers, they exist in some patients and PRLR expression has been implicated in breast oncogenesis." (PMID 21655368, 2008). "In conclusion, our results demonstrate that retinoids are able to inhibit the expression of prolactin receptor message, which encodes an important growth factor receptor in breast cancer cells." (PMID 9888458, 1999).
breast cancer (continued). "Thus, 20 normal variants in the PRLR gene were investigated in 1701 breast cancer patients with different treatments." (PMID 40723262, 2025). "This could lead to the better effect of radiotherapy treatment against breast cancer if the tumor has low PRLR expression or if the patient carries certain PRLR normal gene variants." (PMID 40723262, 2025). "PRLR (Prolactin Receptor) is a receptor for prolactin and type I cytokine, which is associated with various physiological and pathological processes, including breast cancer, mammary gland development, reproductive regulation, and immune regulation." (PMID 39201769, 2024). "In addition, the expression of the Prolactin receptor in primary breast cancer is associated with poor prognosis, due to accelerated progression and bone osteolytic metastasis development." (PMID 36499741, 2022). "Furthermore, PRLR expression was significantly associated with better survival outcome in breast cancer cases." (PMID 36157462, 2022). "PRLR is a type 1 cytokine receptor implicated in the initiation and progression of breast cancer." (PMID 34107902, 2021). "Next, to investigate whether loss of PRLR expression in HER2-E breast cancer cells affect their luminal differentiation state, we examined expression of the luminal marker CK18." (PMID 33446633, 2021). "Loss of PRLR expression in HR+ breast cancer cells caused their dedifferentiation generating a mesenchymal-basal-like phenotype enriched in CD44+ breast cancer stem-like cells (BCSCs) showing high tumorigenic and metastatic capacities and resistance to anti-hormonal therapy." (PMID 33446633, 2021). "To further examine the impact of loss of PRLR expression on the differentiation state of the HR+ MCF-7 breast cancer cells, we used immunofluorescence confocal microscopy to assess the expression pattern of the mesenchymal and EMT markers, vimentin and the transcription factor Snail." (PMID 33446633, 2021). "Whereas loss of PRLR expression in HER2-E breast cancer cells resulted in loss of their luminal differentiation yet enriched for epithelial ALDH+ BCSC population showing elevated HER2-driven tumorigenic, multi-organ metastatic spread, and resistance to anti-HER2 therapy." (PMID 33446633, 2021). "In addition to mammary carcinoma, PRLR signaling is also implicated in the development of prostate, colon, ovarian and endometrial cancers." (PMID 34572912, 2021). "Beyond its recognized role in the development and differentiation of the normal breast, prolactin causally contributes to the pathogenesis of breast cancer via an autocrine/paracrine loop involving prolactin binding to its membrane-associated prolactin receptor (PRLR)." (PMID 33335078, 2020). "Although PRLR signalling has been traditionally involved in tumourigenesis of the mammary gland, it has been recently associated to the inhibition of breast cancer invasion, and a protective role of PRLR/STAT5 signalling has been proposed in already established tumours." (PMID 31862900, 2019). "PRLR is a type 1 cytokine receptor that has been implicated in the pathology of breast cancer." (PMID 29262565, 2017). "In addition of the known primary physiological role of PRLR activation by its cognate hormone in growth and differentiation of mammary gland and lactation, it mediates the development and progression of breast cancer and causes chemoresistance." (PMID 27564112, 2016). "Furthermore, elevated circulating PRL levels have been positively correlated with breast cancer metastasis and PRLR-deficient mice have prevention of neoplasia progression into invasive carcinoma." (PMID 27542844, 2016). "Low ratios of short forms to the long-form of the PRLR are associated with mammary carcinoma." (PMID 27564112, 2016). "I146L and I76V polymorphisms were not genotyped in the Polish Breast Cancer Study, but these loci may represent appealing targets for future research into PRLR genetic variation and breast cancer risk." (PMID 21470416, 2011).
breast cancer (continued). "Few studies have investigated the association between SNPs in PRL and PRLR and breast cancer risk." (PMID 21470416, 2011). "Thus, we examined the relationship between single nucleotide polymorphisms (SNPs) in PRL and PRLR, serum prolactin levels and breast cancer risk in a population-based case-control study." (PMID 21470416, 2011). "PRLR SNPs rs7718468 and rs13436213 and a haplotype including PRLR SNPs rs873456, rs7718468, rs34024951, and rs9292575 were associated with breast cancer in postmenopausal women; however, the SNP associations were not statistically significant after adjustment for multiple comparisons." (PMID 21470416, 2011). "Therefore, our primary aim was to investigate whether PRLR genetic variants could serve as treatment-predictive factors in a cohort of women diagnosed with primary breast cancer." (PMID 40723262, 2025). "Therefore, in a case–control study nested in the NHS, we examined the association between circulating prolactin levels measured 10 or fewer years prior to diagnosis and risk of breast cancer by tumor expression of the PRLR, pSTAT5, and phosphorylated JAK2 (pJAK2)." (PMID 36882838, 2023). "Moreover, genomic analysis of mammary tumors arising in the 129:Stat1−/− mouse established they almost always harbored a truncating exon 10 mutation of the prolactin receptor (PRLR) that was tumorigenic when heterozygously expressed in embryonic fibroblasts lacking Stat1 but overexpressing Jak2." (PMID 28865492, 2017). "Exploration of genetic variants in PRL and PRLR has identified single-nucleotide polymorphisms (SNPs) that alter transcription factor binding, modify prolactin receptor activity, and may be associated with breast cancer risk or circulating prolactin levels." (PMID 21470416, 2011). "We observed significant interactions between specific combinations of PRLR SNPs (AG/GG/TT/CC/TC) and radiotherapy in relation to clinical outcomes in a population-based cohort of women diagnosed with breast cancer." (PMID 40723262, 2025). "For example, preclinical studies demonstrate a superior killing effect with a bispecific ADC targeting both HER2 and prolactin receptor in breast cancer cells that co-express each target due to the enhanced internalization of prolactin receptor." (PMID 41334034, 2025). "The prolactin (PRL) receptor (PRLR), known to play a role in metastasis, is another contributing factor to patient prognosis in breast cancer." (PMID 40723262, 2025). "To elucidate the role CCN2 in regulating/altering PRL/PRLR effects in mammary and breast cancer cells, we first generated CCN2 physical interaction gene network." (PMID 40157909, 2025). "To further dissect the role and contribution of the PRL/PRLR pathway in regulating differentiation in breast cancer, we made use of the CRISPR/Cas9 knockout of the PRLR in MCF7 cells (MCF7/PRLR-KO) previously generated." (PMID 40157909, 2025). "Together, these results highlight a crucial interconnection between PRLR expression and the anti-tumorigenic Hippo/polarity pathway, demonstrating its significant and vital positive clinical impact on patient outcomes in breast cancer." (PMID 40157909, 2025). "We retrieved 158 genes from the KEGG database and performed a pathway-centric co-expression analysis with PRLR gene using Pearson correlation in the SCAN-B breast cancer dataset." (PMID 40157909, 2025). "Prolactin receptor (PRLR) signaling affects breastfeeding and potentially breast cancer treatment response." (PMID 40723262, 2025). "For example, a study reported an immunotoxin targeting PRLR to enhance tamoxifen sensitivity and chemotherapy efficacy in breast cancer." (PMID 40978029, 2025). "RNA-Seq data analysis of CRISPR/Cas9 knockout of the PRLR in HR+ breast cancer cells revealed the oncogenic CCN2 gene as the most upregulated target gene, highlighting an antagonistic relationship between PRLR and CCN2 gene expression." (PMID 40157909, 2025).